BCL9 (BCL9 transcription coactivator)
Diseases named in the same sentence as BCL9 in open-access papers (continued):
Sharing a sentence is not in itself a finding about the gene and the disease.
cancer (74 papers, 2008 to 2025). A tumor composed of atypical neoplastic, often pleomorphic cells that invade other tissues. "Collectively, such data indicate that BCL9 expression is negatively associated with antigen presentation and immune infiltration in cancers." (PMID 38811552, 2024). "Together, these studies suggest that both BCL9/9l and Pygo1/2 are attractive therapeutic targets in cancers that harbour mutations in both APC and CTNNB1." (PMID 37048063, 2023). "BCL9 is a well-recognized oncogene that acts as a transcriptional co-activator of the Wnt/β-catenin pathway and has been implicated in a variety of cancers." (PMID 35368023, 2022). "detected that knock down of nuclear BCL9 promoted tumorigenesis in murine cancer-associated fibroblasts (CAFs), whereas aberrant inactivation of Wnt/β-catenin due to BCL9 suppression aided T-cell–mediated antitumor immune responses." (PMID 36032085, 2022). "We found that the loss of Pygopus 2-B9/B9L binding in cancer cells expressing the ΔHD1 mutant forms of Bcl9/9L results in smaller tumors and less metastases." (PMID 34545187, 2021). "B-cell lymphoma 9 (BCL9) is an oncogenic factor and its upregulation is associated with poor prognosis of patients with cancer, low incidence of apoptosis in cancer cells, and increased malignancy." (PMID 32503307, 2020). "This chromosomal translocation causes the uncontrolled expression of BCL9, which becomes a vital part of the pathogenesis of malignant tumors." (PMID 31827404, 2019). "Since BCL9 proteins are implicated in cancer development and progression, we analyzed their expression and role in normal and malignant breast tissues." (PMID 25149534, 2014). "Thus, our findings offer some insights into enhancing the susceptibility of tumors with high BCL9/BCL9L expression to cancer immunotherapy." (PMID 38811552, 2024). "Interestingly, BCL9 belongs to a small subset of 1q genes that were also found to be overexpressed and upregulated in group D, a cancer group bearing 16q-loss and 1q-disomy." (PMID 33808143, 2021). "Moreover, loss of BCL9/9l suppresses CRC development driven by Wnt pathway effectively in murine models that resembling human cancer." (PMID 33552975, 2020). "Importantly, loss of BCL9/9l is particularly effective at blocking colonic tumourigenesis and mutations that most resemble those that occur in human cancer." (PMID 30760720, 2019). "Overexpression of BCL9 may have pathogenic significance in malignant neoplasms of B cells." (PMID 35328011, 2022). "BCL9 functions as a coactivator of Wnt/β-catenin-dependent transcription, driving cancer progression through the activation of genes involved in crucial developmental processes." (PMID 40362354, 2025). "This is important, as, if TBX3 proved to be dispensable for homeostasis as BCL9/9L but required for cancer cell survival as TBX5 or β-catenin, its targeting will constitute the proverbial therapeutic window." (PMID 40343989, 2025). "Amazingly, our findings uncovered that targeting BCL9/BCL9L can excellently enhance antigen presentation in cancers." (PMID 38811552, 2024). "BCL9 is considered a key developmental regulator and a well-established oncogenic driver in multiple cancer types, mainly through potentiating the Wnt/β-catenin signaling." (PMID 39200196, 2024). "In support of these findings, we characterized the datasets of cancer patients from TCGA with either low or high BCL9 mRNA expression." (PMID 38811552, 2024). "Given these factors, many efforts have been made for the development of bioactive peptides that block the β-catenin/Bcl9 interaction in cancer therapy, for instance, hsBCL9CT-24, sulfono-γ-AA, and ECRV." (PMID 35745877, 2022). "Hypoxia and HIF1α activate Wnt/β-catenin signaling via the expression of BCL9, resulting in cancer cell proliferation and metastasis." (PMID 35027586, 2022).
cancer (continued). "We demonstrated that the cell type balance and transcription differences of TAMs regulated by BCL9-driven Wnt signaling affected immune surveillance and inflammation of cancer, ultimately affecting patients’ prognosis." (PMID 34566638, 2021). "Our findings have highlighted the potential of targeting the BCL9-driven Wnt signaling pathway in TMAs in cancer immunotherapy." (PMID 34566638, 2021). "B-cell lymphoma 9 (BCL9), a key transcription co-activator of the Wnt pathway, is highly expressed in cancers." (PMID 34417435, 2021). "But the genomic region containing human BCL9 (1q21) is amplified in several cancers, and this correlates with poor clinical outcomes." (PMID 33085215, 2021). "The third differentially methylated region was BCL9; its promoter was found to be significantly hypermethylated in cancer patients compared to healthy controls." (PMID 34452548, 2021). "In summary, we demonstrate cell type landscape and transcription difference upon BCL9 suppression in CAFs, as well as how CAF affects cancer associated immune surveillance by inhibition of Wnt signaling." (PMID 34026600, 2021). "The oncogene BCL9 functions as a transcriptional co-activator of the Wnt/β-catenin signaling pathway in cancer." (PMID 34277614, 2021). "In this study, we demonstrated that the cellular landscape and transcription differences of TAMs after BCL9 suppression affected cancer and immune surveillance." (PMID 34566638, 2021). "In this project, we also will use the BCL9-endo-Score to score all of the cancer samples in the TCGA database." (PMID 33552975, 2020). "In the TCGA database, we found that the high BCL9-endo-Score indicates a good prognosis in three cancers: COAD, CESC and OV." (PMID 33552975, 2020). "So far, miR-30c has been reported to be targeted and regulated by the transcription factors including Myc, HMBOX1 and C/EBP alpha with the target of miR-30cincludingMTA1, KRAS, BCL-9,Notchand cancer cell invasion related genes including TWF1, VIM and CCND2." (PMID 32201529, 2020). "The GSEA indicated that samples with high BCL9 expression were also significantly enriched in the Wnt signaling pathway and the pathways in cancer." (PMID 31827404, 2019). "Some small-molecule inhibitors that target the interface between BCL9 and β-catenin have been extensively studied recently in colorectal cancer cells, which has provided hope to the clinical treatment of malignant tumors." (PMID 31827404, 2019). "BCL9 functions as coactivator of β-catenin, and in fact, the Wnt/β-catenin pathway appears dysregulated in various cancer types." (PMID 30197759, 2018). "The inhibitors of the protein–protein interactions, bromodomains, and the β-catenin/B-cell lymphoma 9 (BCL9) interaction were used to examine the protocol, and the cellular bioavailability of the inhibitors in cancer cells was determined." (PMID 27935314, 2017). "By exome sequencing, we identified novel, frequent frameshift mutations in four cancer-critical genes (CRTC1, BCL9, JAK1, and PTCH1)." (PMID 28539123, 2017). "It will be interesting to test experimentally the putative roles of BCL9/B9L and Pygo in enabling cross-talk between β-catenin and nuclear hormone receptor signaling, both during normal development and in cancer." (PMID 28296634, 2017). "As a result, BCL9-inhibited cancer cells became more sensitive to PD-1 inhibitors." (PMID 40362354, 2025). "We note this narrower CNA segment does not include the MDM4 oncogene, which is located at 1q32.1, thus other genes must be driving this recurrent genetic change in CNA-PC86, with possible candidates being known cancer genes BCL9 (1q21.2), ARNT (1q21.3), SETDB1 (1q21.3), or SF3B4 (1q21.2)." (PMID 41023738, 2025). "Moreover, cancer patients with high BCL9 expression had significantly worse overall survival than those with low BCL9 expression among the tumors exhibiting low immune infiltration, especially among those also displaying Wnt activity." (PMID 38811552, 2024).
cancer (continued). "Additionally, Bcl9 is overexpressed in carcinoma, and its deletion can safely suppress tumorigenesis and invasion in β-catenin-dependent cancer models." (PMID 35745877, 2022). "Key roles of CD155-CD226 and CD155-CD96 checkpoints in cancer cell/CD8+ T cell interactionPhosphorylation of VAV1 in CD8+ T cells via BCL9 suppression, mediating Wnt transcriptionUpregulation of GLI1 and PATCH expression in promoting CD155 expression in cancer cells." (PMID 36032085, 2022). "Thus, hypoxia and HIF1α activate Wnt/β-catenin signaling via BCL9, resulting in cancer cell proliferation and metastasis." (PMID 35027586, 2022). "Previous studies have examined the role of BCL9 in cancer, including HCC." (PMID 34978646, 2022). "In The Cancer Genome Atlas database analysis, we found that BCL9 expression is positively associated with CD155 and negatively associated with CD226 expression." (PMID 34417435, 2021). "Since our analysis revealed an overexpression of BCL9 in estrogen-receptor positive Lum A cancers, it is possible that BCL9 interacts with proteins other than β-catenin, and its activity may be, in part, independent of Wnt/β-catenin." (PMID 33808143, 2021). "In mouse model of CRC, BCL9 and its paralogue BCL9L promote both early stages of carcinogenesis, as well as late‐occurring traits associated with EMT and cancer metastasis." (PMID 33085215, 2021). "Finally, in the TCGA database, at the pan-cancer scale, we found that BCL9-endo-Score can predict the prognosis of one type of special marker tumors well." (PMID 33552975, 2020). "Even though the role of BCL9 in the Canonical Wnt cascade was previously demonstrated, there is limited research on which specific Wnt targets are regulated by BCL9 and whether BCL9 regulates other signaling pathways to drive cancer malignancy." (PMID 32352029, 2020). "Oncogenic BCL9 proteins represent promising targets for cancer therapy and inhibiting them may be particularly beneficial in Wnt-inactive HCCs." (PMID 31440992, 2020). "In CA-treated mice, we found decreased nuclear expression of BCL9 and β-catenin, which suggests that the anti-cancer effect of carnosic acid could depend on its ability to degrade BCL9 and β-catenin proteins." (PMID 32352029, 2020). "Bcl9 could also modulate interactions of β-catenin to improve EMT and invasion, and was associated with poor outcome in cancer." (PMID 31920959, 2019). "To investigate whether the HMA-resistance-specific CNAs influence gene expression, we assayed the expression of 8 cancer-related genes by quantitative reverse transcription PCR (RT-qPCR) including BCL9, ARNT, ABL2, STK11, TCF3, SMARCA4, RUNX1, and U2AF1." (PMID 28052028, 2017). "The role of BCL9 in the progression of other types of cancers has been reported previously." (PMID 26384318, 2015). "Also, other studies have examined the role of BCL9 in cancer, including HCC." (PMID 34978646, 2022). "Hence, we hypothesised that the larger the APC protein and therefore more β-catenin binding activity that is retained, the more dependent cancer cells would become upon BCL9/9l for Wnt driven transformation." (PMID 30760720, 2019). "Indeed, they include also LAD1 and BCL9, known to be involved in cancer invasiveness." (PMID 29017520, 2017). "This study investigates the potential of BCL9 and TPX2, two proteins involved in cancer progression, to predict patient outcomes This study analyzed protein abundance data from the CPTAC cohort (110 ccRCC and 84 NAT samples) using LC-MS/MS." (PMID 40362354, 2025). "Therefore, our study may also provide a novel mechanism for targeting Wnt/β-catenin signaling to promote antitumor immunity by overcoming cDC1 dysfunction in TME, suggesting that targeting BCL9/BCL9L to improve NF-κB-dependent antigen presentation in tumors is a potential approach to cancer therapy." (PMID 38811552, 2024).
cancer (continued). "The 1q+ tumors of EX3 share overexpression of seven cancer genes e.g., BCL9 and SETDB1, whilst EX1 1q+ tumors share only MDM4 overexpression and overexpress fewer cancer genes overall." (PMID 36230794, 2022). "Real-time PCR was performed to check the methylation difference of HOXD9, ZNF154, BCL9, TDRD10, and ANKRD53 genes between the cancer cases and controls." (PMID 34452548, 2021). "BCL9 suppression blocks VAV1 phosphorylation in CD8+ T cell as well as increases GLI1 and PATCH expression to promote CD155 expression in cancer cells." (PMID 34417435, 2021). "Some of the specific transcripts observed included those from the well-established cancer survival genes ALDH1A1, SURVIVIN, XIAP, HSPG2, BCL9, and SOX4." (PMID 34579762, 2021). "BCL9 suppression induces phosphorylation of VAV1 in CD8+ T cells and increases GLI1 and PATCH expression to promote CD155 expression in cancer cells." (PMID 34417435, 2021). "We also analyzed a panel of putative cancer-related genes, including CDK8, MITF, SMAD7, KLF12, AG02, CDK14, and BCL-9, but only PTEN expression was shown to be significantly altered by miR-216a overexpression." (PMID 30061175, 2018). "Third, in the hsBCL9CT-24 treated CT26/MC38 model, hsBCL9CT-24, which is a BCL9 and β-cat inhibitor, suppressed transcription of Wnt signaling both in immune cells and cancer cells, without depleting or knockout BCL9 and β-cat protein." (PMID 34417435, 2021). "It appears conceivable that up-regulation of miR-576-5p might rescue the cancer cell from apoptosis, e.g. by up-regulation of MCL1 and BCL9, thereby increasing its invasive phenotype." (PMID 30197759, 2018). "So far, transcriptional regulation of BCL9-2 has not yet been studied in detail, although we have previously shown that the BCL9 and Pygo genes are not Wnt/ß-catenin targets in cancer cells." (PMID 25149534, 2014). "Targeting BCL9/BCL9L to regulate cDC1 function and directly orchestrate a positive feedback loop necessary for optimal antitumor immunity could serve as a potential strategy to counter immune suppression and enhance cancer immunotherapy." (PMID 38811552, 2024). "There are a number of reports about BCL9 role in non-immune regulation in cancer development." (PMID 34417435, 2021). "We first evaluated whether in fetal‐like HB cell lines, the partial deletion of CTNNB1 exon 4 could alter the capability of β‐catenin to interact with BCL9 and BCL9L, which are established co‐activators of the Wnt pathway important to specify a stem cell‐like phenotype in cancer cells." (PMID 28923827, 2017). "Importantly, BCL9 is absent from tumors originating from normal cellular counterparts and overexpressed in many cancers including HCC." (PMID 28074862, 2017).
infection (4 papers, 2017 to 2023). The state of being infected such as from the introduction of a foreign agent such as serum, vaccine, antigenic substance or organism. "Floxed alleles of Bcl9, Bcl9L, and β-catenin genes were recombined by infection with Adenovirus expressing Cre-recombinase and GFP (Ad-Cre-IRES-GFP)." (PMID 34545187, 2021). "SARS-CoV-2 infection caused overexpression of BCL9 and underexpression of ACTR2 after 24 h of infection of the cells." (PMID 37211584, 2023). "SARS-CoV-2 infection caused overexpression of BCL9 and underexpression of ACTR2 in infected cells after 24 h post-infection." (PMID 37211584, 2023). "However, for induction of the BCL9 gene, infection is not required, and transcription can be stimulated by simply exposing the cells to C. burnetii bacterial antigens." (PMID 37285354, 2023). "Notably, BCL9, WntA3, and FDZ1 genes were significantly overexpressed where cells were infected with the live and more virulent Guiana strain of C. burnetii compared to infection with the live Nine Mile strain." (PMID 37285354, 2023).
adenocarcinoma (1 paper, 2012). A common cancer characterized by the presence of malignant glandular cells. "BCL9 is a novel oncogene in Wnt signaling pathway, playing a critical role in epithelial-mesenchymal transition in colon epithelium and adenocarcinomas." (PMID 23078675, 2012).
benign tumor (1 paper, 2019). "The positive BCL9 expression rates in ovarian epithelial malignant, borderline, and benign tumor tissues and normal ovarian tissues were 81.97%, 76.92%, 38.46%, and 0%, respectively." (PMID 31827404, 2019).
colon polyps (1 paper, 2024). "This is the first study analyzing the gene expression of APC, Wnt3A, Wnt5A, BCL9, and LEF1 in the colon polyps vs. adjacent mucosa and vs. normal mucosa from control individuals." (PMID 39200196, 2024).
BCL9 also shares sentences with these, for which no sentence is quoted: lung carcinoma (4 papers); acute lymphoblastic leukemia (3); bipolar disorder (3); breast ductal carcinoma (2); ductal carcinoma in situ (2); glioma (2); kidney cancer (2); acute B-cell precursor lymphoblastic leukemia (1); Acute myelogenous leukemia (1); alopecia (1); attention deficit-hyperactivity disorder (1); B Cell CLL (1); brain tumors (1); Clear Cell Renal Cell Carcinoma (1); congenital hypothyroidism (1); depression (1); diffuse large B-cell lymphoma (1); esophageal cancer (1); gastritis (1); Hand-foot syndrome (1); head and neck cancer (1); hepatitis B infections (1); hepatitis C- (1); invasive carcinoma (1); invasive ductal breast carcinoma (1); lung adenocarcinoma (1); lung squamous cell carcinoma (1); meningioma (1); non-small cell lung carcinoma (1); ovarian endometriosis (1).
A further 4 diseases each share a sentence with BCL9 in 1 paper.